LTBP2 (latent transforming growth factor beta binding protein 2)
Diseases named in the same sentence as LTBP2 in open-access papers (continued):
Sharing a sentence is not in itself a finding about the gene and the disease.
tumor (26 papers, 2011 to 2025). "While observed to have both tumour suppressing and tumour promoting functions, up-regulation of LTBP2 has been associated with poorer patient outcomes in certain cancers." (PMID 41270070, 2025). "The corollary of these findings indicates that the ECM LTBP2 protein plays crucial roles in the tumor microenvironment and are implicated in the critical NF-κB p65 signaling cascade in NPC." (PMID 25974126, 2015). "Collectively, these data confirm the importance of LTBP2 in suppressing tumor-associated angiogenesis in NPC through significant reduction of pro-angiogenic factors." (PMID 25974126, 2015). "More importantly, the analysis of LTBP2 in tumor biopsies may hold potential prognostic or diagnostic value in a clinical perspective." (PMID 25974126, 2015). "Since silencing of LTBP2/3 can bypass senescence in HMF3A cells, it suggests that LTBP2/3 may be linked with the control of cell growth and be playing a role in suppressing tumour progression perhaps through regulation of TGFβ." (PMID 21740549, 2011). "Further, analysis of the association between those ECM components and GC clinicopathological features revealed that increased expression of COL1A2, LOX and LTBP2 significantly correlated with high tumor stage." (PMID 35340765, 2022). "Univariate analysis showed high LTBP2 expression, tumor node metastasis stage, T stage, and N stage were prognostic factors of patients with tumors." (PMID 35512078, 2022). "More and more evidences indicate that LTBP2 plays an important role in tumor genesis and development." (PMID 35968244, 2022). "At the same time, LTBP2 has been established as a prognostic marker for diverse cancer types and can control tumor cell sensitivity to immunotherapy." (PMID 32802850, 2020). "For example, LTBP2 was more downregulated in NPC tumor tissues than in matched normal tissues and played a suppressive role in tumor development and progression." (PMID 30956730, 2019). "LTBP2 protein expression was also higher in CRC tissues than in matched tumor-adjacent tissues and benign colorectal diseases." (PMID 30956730, 2019). "In ESCC, both tumor suppressing and tumor promoting functions have been observed for LTBP2: it was epigenetically downregulated in tumor tissues compared to normal tissues; however, low tumor cell LTBP2 expression predicts better overall survival." (PMID 27281608, 2016). "Re-expression of LTBP2 elicits tumor suppressive effects that parallel the inactivation of p65 in NPC cells." (PMID 25974126, 2015). "Of the 9 genes tested, 8 (THBS1, CYR61, CTGF, MXRA5, SPP1, LTBP2, TGFBR1 and COL11A1) were found by qRT-PCR to be significantly differentially expressed in tumor-associated fibroblasts, for a validation rate of 89%." (PMID 26575166, 2015). "Conversely, exosomes derived from tumor-associated macrophages led to increased expression of TGF-β signaling pathway activators in meningioma cells, specifically TGFBI, SNAI1, MMP2, TGF-β1, TGF-β2, IGFBP7, and LTBP2, leading to tumor cells obtaining a more aggressive phenotype." (PMID 40486962, 2025). "LTBP2 gene expression levels rose with escalating tumor stage." (PMID 38577985, 2024). "The positive staining of LTBP2 was mainly localized in the cytoplasm of tumor cells." (PMID 30956730, 2019). "Previously, we identified an ECM protein, LTBP2, as a candidate tumor suppressor in NPC." (PMID 25974126, 2015). "From another perspective, our results suggest that the high expression of LTBP2 in GC may be one of the mechanisms of self-protection, maintaining tumor proliferation by avoiding ferroptosis, and the results are also consistent with the research that Nrf2 can regulate ferroptosis." (PMID 35968244, 2022). "In recent years, more and more studies have found that LTBP2 expression is increased in a variety of malignant tumors, such as nasopharyngeal cancer, esophageal cancer, melanoma, cervical cancer, etc., and its overexpression is significantly related to tumor progression and poor prognosis." (PMID 35968244, 2022).
tumor (continued). "Upon analyzing the expression of 11 model genes in prostate PRAD, we observed significant differential expression of eight genes (MYADM, MPDZ, LTBP2, DENND4C, PROK1, DDIT4, IGFBP3, and CFD) between normal and tumor tissues." (PMID 38898043, 2024). "Latent transforming growth factor beta‐binding protein 2 (LTBP2), a member of the extracellular matrix (ECM) glycoprotein superfamily, plays a regulatory role in the ECM and impacts tumor progression." (PMID 39485722, 2024). "In particular, we noticed that COL1A2, LAMB3, LOX, LTBP2 and S100A6 were significantly upregulated in tumor specimens, when compared with normal tissue." (PMID 35340765, 2022). "Consistent with what we observed for LOX and LTBP2, we found that COL10A1, which was the only tumor-specific protein, is strongly increased in tumor tissue (p = 5.93e-06), when compared with paired normal adjacent mucosa." (PMID 35340765, 2022). "We detected the mRNA expression of LTBP2 in 28 cases of fresh CRC tissues and 4 CRC cell lines and the protein expression of LTBP2 in 483 samples of CRC tissues, matched tumor-adjacent tissues, and benign colorectal diseases." (PMID 30956730, 2019). "LTBP-2, a type of extracellular matrix (ECM) protein, decreases the colony-forming abilities of ESCC and induces tumor suppression." (PMID 25823933, 2015). "Overexpression of LTBP-2 induced dormancy and inhibited NPC cell migration and angiogenesis through the reduction of VEGF, which led to attenuated tumor formation." (PMID 24502434, 2013). "Importantly, the expression of COL1A2, LOX and LTBP2 significantly correlated with high tumor stage, with LOX and LTBP2 further impacting patient overall survival." (PMID 35340765, 2022). "Likewise, TGF-beta binding (TB) domain superfamily (LTBP1, LTBP2, FBN2; p = 4.76e-06) was over-represented in upregulated tumor ECM proteins." (PMID 35340765, 2022). "In this study, we determined both the mRNA and protein expression levels of LTBP2 in CRC tissues and matched tumor-adjacent tissues by quantitative real-time polymerase chain reaction (qRT-PCR) and tissue microarray immunohistochemistry (TMA-IHC) analyses, respectively." (PMID 30956730, 2019). "Interestingly, increased mRNA expression was already observed in normal tissue of tumor patients compared to healthy donors for THBS2, SPARC, LTBP2 as well as the collagens COL8A1 and COL12A1." (PMID 29176937, 2017). "Therefore, it is not difficult to guess that LTBP2 also has bilateral effects towards tumor development." (PMID 30956730, 2019). "Thus it is not surprising that both tumor promoting and tumor suppressing functions have been proposed for LTBP2." (PMID 27281608, 2016). "Furthermore, LTBP2 is both tumor suppressing and tumor promoting in ESCC, which means that LTBP2 was more downregulated in tumor tissues than in matched normal tissues, but high LTBP2 predicts poor overall survival." (PMID 30956730, 2019).
cancer (20 papers, 2013 to 2025). A tumor composed of atypical neoplastic, often pleomorphic cells that invade other tissues. "At present, increasing reports have shown that latent transforming growth factor-β-binding protein 2 (LTBP2) was associated with the prognosis of many types of cancer." (PMID 35512078, 2022). "Of the included studies for estimating the association between LTBP2 expression and survival of patients with tumors, 7 studies provided 10 sets of comparable data for comparing the LTBP2 expression between carcinoma and adjacent tissues." (PMID 35512078, 2022). "The top-20 DEGs identified in the in vitro BMEC model included transforming growth factor β induced (Tgfbi) and latent Tgfβ binding protein (Ltbp2), which have both been linked to cancer invasion and metastasis." (PMID 31426861, 2019). "The present analysis suggested that LTBP2 may have significant association with survival of patients with cancer." (PMID 35512078, 2022). "The identification of LTBP2 as a direct target offers fresh perspectives for pharmacological intervention against cardiac fibrosis, particularly in cancer therapy." (PMID 41463359, 2025). "We performed rounded analysis to comprehensively analyze and evaluate the prognostic significance of LTBP2 for patients with malignant tumors." (PMID 35512078, 2022). "The odds ratio with its 95% confidence interval (CI) was used to assess the correlation between LTBP2 and clinicopathologic features or overall survival of patients with cancer." (PMID 35512078, 2022). "The insights gained from this research described a new function of LTBP2 in regulating ferroptosis, suggesting that LTBP2 has a broad application prospect in the ferroptosis-mediated malignant tumor therapy." (PMID 35968244, 2022). "Our findings described a new role of LTBP2 in regulating ferroptosis, which heralds the prospect of ferroptosis-mediated cancer therapy." (PMID 35968244, 2022). "Our overall analysis results showed that, compared with normal or adjacent tissues, the incidence of high LTBP2 expression was more than 4 folds in carcinoma tissues, with the pooled OR being 4.38 (95% CI 3.52–5.44; P < .00001)." (PMID 35512078, 2022). "LTBP2 protein levels in cancer tissues were correlated with HNSCC patients' clinical characteristics and overall survival." (PMID 27281608, 2016). "Various functions of LTBP2 have been indicated in different types of cancer." (PMID 32826876, 2020). "Ltbp2 had previously been proposed to be a potential biomarker for atrial stress and was patented as a biomarker for cardiovascular, hematological, neurological, endocrinological, and urological diseases, as well as cancer." (PMID 26822062, 2016). "Detection of LTBP2 expression could be a useful prognosis marker and targeting LTBP2 may represent a novel strategy for cancer treatment through regulating activities of TGFβ." (PMID 27281608, 2016). "In scRNAseq analysis, LTBP1 and LTBP2 were expressed dominantly in CAFs alone, while LTBP4 was strongly expressed in CAFs, in addition to pericytes and cancer cells." (PMID 40075643, 2025). "These criteria identified five initial genes to be screened including LTBP2 (latency TGF-β binding protein 2), a gene previously found to undergo promoter hypermethylation in cancer." (PMID 32503656, 2020). "Although pathological processes are different in cancer and CCM, this purports the role of similar yet novel Tgfbi and Ltbp2 in CCM disease." (PMID 31426861, 2019). "Among them are genes involved in cell adhesion/migration processes (PEPD), migratory potential of cancer cells (ACTN1), ECM (LTBP2, PRG4, ADGRL1, CD9), or in metabolic processes (LDHD, ALDH7A1), as well as proto-oncogenes or their ligands/inhibitors (FYN, PPP1R13L)." (PMID 30838002, 2019).
connective tissue disease (2 papers, 2014 to 2020). "Mutations in human FBN1, FBN2, LTBP2, LTBP3 and LTBP4 have been associated with connective tissue disease in humans." (PMID 24703491, 2014).
genetic disease (2 papers, 2017 to 2023). "Since TGF-β1 plays a key role in the proliferative phase of wound healing and in fibrosis, it is possible that the TGF-β1 upregulation by LTBP-2 in fibroblasts plays some role in fibrotic disease processes and in genetic disorders which have fibrotic components, such as WMS." (PMID 28991210, 2017).
LTBP2 also shares sentences with these, for which no sentence is quoted: megalocornea (4 papers); pulmonary arterial hypertension (3); aniridia (2); chronic lymphocytic leukemia (2); juvenile open angle glaucoma (2); ocular hypertension (2); ovarian carcinoma (2); ascending aortic aneurysm (1); atrial fibrillation (1); blepharospasm (1); brachydactyly (1); cardiac ischemia (1); congenital cataracts (1); congenital heart disease (1); congestive heart failure (1); endometrial cancer (1); Epiphora (1); gastric adenocarcinoma (1); hepatocellular carcinoma (1); hyperopia (1); idiopathic pulmonary fibrosis (1); infarcts (1); interstitial lung disease (1); intraepithelial neoplasia (1); iris hypoplasia (1); laryngeal squamous cell carcinoma (1); metastasis (1); myocardial infarction (1); osteoporosis (1); partial lipodystrophy (1).
A further 15 diseases each share a sentence with LTBP2 in 1 paper.